MBD3L3 (methyl-CpG binding domain protein 3 like 3)
Tractability: No criterion of Open Targets' tractability assessment is met for any kind of drug.
Gene: Protein-coding gene on chromosome 19 (7,056,207 to 7,069,665, reverse strand). Ensembl gene ENSG00000182315.
Subcellular location (Human Protein Atlas): Nucleoli; Nucleoplasm
Gene Ontology:
Molecular function: protein binding; methyl-CpG binding
Biological process: DNA methylation-dependent constitutive heterochromatin formation; negative regulation of transcription by RNA polymerase II
Cellular component: nucleus
Homologues: Orthologues: rat Mbd3l2 (43% identical), rat Mbd3l3 (40% identical), mouse Mbd3l2 (39% identical), zebrafish mbd3a (31% identical), tropical clawed frog mbd3 (30% identical), Drosophila melanogaster MBD-like (22% identical). Paralogues in human: MBD3L4 (99% identical), MBD3L5 (99% identical), MBD3L2 (98% identical), MBD3L2B (97% identical), MBD3L1 (36% identical), MBD2 (32% identical), MBD3 (31% identical), MBD1 (21% identical).
Diseases named in the same sentence as MBD3L3 in open-access papers:
MBD3L3 is named in the same sentence as 1 disease in open-access papers, as found by Europe PMC text mining. Sharing a sentence is not in itself a finding about the gene and the disease.
MBD3L3 shares sentences with these, for which no sentence is quoted: cancer (1 paper).